C1GALT1 (core 1 synthase, glycoprotein-N-acetylgalactosamine 3-beta-galactosyltransferase 1)
Diseases named in the same sentence as C1GALT1 in open-access papers (continued):
Sharing a sentence is not in itself a finding about the gene and the disease.
tumor (continued). "The mRNA expression experiments demonstrated that there were 23% (7/30) of tumor cases showing a high expression of C1GALT1, whereas 77% (23/30) showed a low expression compared with the adjacent normal tissue using a cut-off value of 1.5-fold change." (PMID 35207462, 2022). "In the trans-splenic metastasis model, C1GALT1 silencing significantly suppressed tumor metastasis to liver, enhanced apoptosis, and reduced proliferation." (PMID 35864552, 2022). "Particularly, the in vitro finding that overexpression of C1GALT1 increases the neurite outgrowth of NB cells is consistent with the high expression of C1GALT1 observed in the NB patients with differentiated tumor histology." (PMID 35169131, 2022). "The present study is the first report to show that high C1GALT1 expression correlates with NB tumor differentiation status and predicts better survival outcomes of patients with NB." (PMID 35169131, 2022). "We observed that C1GALT1 expression was upregulated in LUAD tissues compared with adjacent non-tumor tissues." (PMID 34307388, 2021). "A paired student’s t test indicated that C1GALT1 was significantly overexpressed in PDAC compared with adjacent non-tumor tissue." (PMID 33420364, 2021). "Gain- and loss-of-function experiments showed that C1GALT1 promoted LUAD cell proliferation, migration, and invasion in vitro, as well as tumor formation in vivo." (PMID 34307388, 2021). "In this study, we showed that 85% of PDAC tumors exhibited higher C1GALT1 expression levels than their adjacent non-tumor pancreatic tissues." (PMID 33420364, 2021). "Here we showed that C1GALT1 was overexpressed in 85% (107/126) of PDAC tumors compared with adjacent non-tumor tissues." (PMID 33420364, 2021). "In the subcutaneous injection model, C1GALT1 knockdown significantly decreased the tumor weights of HPAF-II cells." (PMID 33420364, 2021). "We found that C1GALT1 overexpression enhanced the tumorigenic abilities of A549 and H1299 cells, as manifested by increased tumor size, volume, and weight." (PMID 34307388, 2021). "In subcutaneous and pancreatic orthotopic injection models, C1GALT1 knockdown decreased tumor growth and metastasis of PDAC cells in NOD/SCID mice." (PMID 33420364, 2021). "Core 1 β 1, 3-galactosyltransferase 1 (C1GALT1), an enzyme highly expressed in various cancers, is correlated with tumor initiation and development." (PMID 34307388, 2021). "In this study, we demonstrated that miR-181d-5p acted as a tumor suppressor in LUAD by targeting C1GALT1." (PMID 34307388, 2021). "This study demonstrates that knockdown of C1GALT1 is sufficient to suppress tumor growth and invasiveness in vitro and in vivo, implying that C1GALT1 is a potential therapeutic target for PDAC treatment." (PMID 33420364, 2021). "Consistent with clinical analysis indicating that lower C1GALT1 expression is associated with better overall survival in PDAC patients, reducing C1GALT1 expression using siRNA suppressed tumor growth and metastasis of PDAC cells." (PMID 33420364, 2021). "The results showed that the promotive effects of C1GALT1 overexpression on tumor growth were weakened by integrin α5 inhibition." (PMID 34452648, 2021). "C1GALT1 knockdown suppressed cell viability, migration, and invasion, as well as decreased tumor growth and metastasis." (PMID 33420364, 2021). "In the orthotopic injection model, 14 weeks after HPAC cells were injected into the pancreas of mice, C1GALT1 knockdown decreased the tumor weights in the pancreas and inhibited metastases to the liver, lungs, and peritoneum." (PMID 33420364, 2021). "Overexpression of C1GalT1 in cancer cells, which increases cellular TF expression, thus aids circulating tumor cell hematogenous dissemination in metastasis by enhancing tumor cell interaction with galectins." (PMID 34944925, 2021). "We found that C1GALT1 mRNA in GC tissues displayed higher levels than in matched adjacent non-tumor tissues." (PMID 34452648, 2021).
tumor (continued). "C1GALT1 affected cell viability, proliferation, invasion, tumor growth, and lung metastasis in HNSCC cells." (PMID 32075174, 2020). "H&E staining of the lung sections revealed that C1GALT1 knockdown decreased the number of metastatic tumor nodules in the lungs." (PMID 32005975, 2020). "Results showed that C1GALT1 knockout significantly decreased the number of MKN45 tumor nodules and total tumor weights in the peritoneal cavity of NOD/SCID mice." (PMID 32005975, 2020). "We found that silencing of C1GALT1 significantly decreased tumor sizes and tumor weights in NOD/SCID mice subcutaneously injected with AGS cells." (PMID 32005975, 2020). "To confirm the public complementary DNA microarray data, we performed western blot analysis and found that C1GALT1 is significantly overexpressed in HNSCC tissues compared with adjacent non-tumor parts (n = 8)." (PMID 29930379, 2018). "To evaluate the effect of C1GALT1 on tumor growth and metastasis, we performed a mouse xenograft model by injecting SAS cells into NOD-SCID mice subcutaneously or through the tail vein, respectively." (PMID 29930379, 2018). "In mouse models, we demonstrate that targeting C1GALT1 with genetic or small molecule approach significantly inhibits HNSCC tumor growth." (PMID 29930379, 2018). "In HNSCC cells, C1GALT1 promotes malignant phenotypes, including cell viability, migration, invasion, tumor growth, and metastasis." (PMID 29930379, 2018). "The results showed that tumor growth was significantly increased in C1GALT1 overexpressing SAS cells and significantly decreased in C1GALT1 knockdown OEC-M1 cells compared with their controls." (PMID 29930379, 2018). "To evaluate the effect of C1GALT1 and itraconazole on tumor growth, we performed a mouse xenograft model." (PMID 29930379, 2018). "Nonetheless, we observed that itraconazole significantly inhibited tumor growth and C1GALT1 expression in control group." (PMID 29930379, 2018). "Our results show that knockdown of C1GALT1 suppressed tumor growth and tumor weight in T47D cells compared with control." (PMID 25762620, 2015). "Spearman Rank Correlation analysis reveals that high C1GALT1 expression correlates with higher histological grade and advanced tumor stage." (PMID 25762620, 2015). "Consistent with in vitro cell growth analyses, these results suggest that C1GALT1 expression can promote tumor growth in vivo." (PMID 25762620, 2015). "C1GALT1 knockdown and overexpression in tumor xenografts were confirmed by immunohistochemistry and Western blotting." (PMID 25762620, 2015). "H&E staining confirmed the location of tumors in the lung sections, and immunohistochemical results confirmed the overexpression or knockdown of C1GALT1 in HCC metastatic tumor nodules." (PMID 25089569, 2014). "We previously reported that core 1 β1,3-galactosyltransferase (C1GALT1) is frequently overexpressed in HCC tumors and its expression is associated with advanced tumor stage, metastasis, and poor survival." (PMID 25089569, 2014). "We recently reported that up-regulation of C1GALT1 modulates O-glycosylation in HCC cells and C1GALT1 expression is associated with advanced tumor stage, metastasis, and poor prognosis in HCC." (PMID 25089569, 2014). "We investigated whether C1GALT1 contributed to drug resistance and tumor growth in OS cells through the ABCC1 pathway." (PMID 39844613, 2025). "Overall, these findings support a hypothesis that C1GALT1 may contribute to enhanced tumor proliferation through transcriptional co‐regulation or downstream glycosylation‐dependent signaling mechanisms." (PMID 40548474, 2025). "C1GALT1 has garnered attention in oncology due to its role in tumor development." (PMID 39844613, 2025). "Further functional validation using in vitro and in vivo models will be essential to confirm whether C1GALT1 plays a direct mechanistic role in tumor progression, immune modulation, or metastasis." (PMID 40548474, 2025).
tumor (continued). "In these cases, increased C1GALT1 expression correlated with a higher abundance of Tregs and MDSCs, suggesting a potential immunosuppressive role for C1GALT1 that could facilitate tumor evasion from immune surveillance." (PMID 40548474, 2025). "These same cancers also exhibited elevated C1GALT1 expression in tumor tissues, suggesting that hypomethylation may contribute to increased gene expression—consistent with the general understanding that DNA methylation typically represses transcription." (PMID 40548474, 2025). "Together, these correlative patterns between methylation status and gene expression across various tumor types suggest that DNA methylation may play a regulatory role in C1GALT1 expression in cancer." (PMID 40548474, 2025). "Furthermore, IHC staining revealed that ABCC1 was predominantly localized in the Golgi apparatus of C1GALT1 knockdown tumor cells, consistent with our in vitro findings." (PMID 39844613, 2025). "Later, to understand the effect of the C1GalT1 gene expression level on tumor proliferation, the expression levels of the C1GalT1 and MKI67 genes were compared across various cancer types, and the relationship between the C1GalT1 expression levels was analyzed." (PMID 40548474, 2025). "Additionally, C1GALT1 gene expression levels were compared between normal and tumor tissues using the TIMER2.0 portal to validate the findings from the Xena portal." (PMID 40548474, 2025). "Our pan‐cancer analysis suggests that C1GALT1 is differentially expressed and epigenetically regulated across tumor types and may contribute to tumor proliferation, metastasis, and immune modulation." (PMID 40548474, 2025). "Cancer types with statistically significant differences in C1GalT1 gene expression between tumor and normal tissues were further analyzed to determine whether changes in DNA methylation could explain these differences." (PMID 40548474, 2025). "Our findings reveal a consistent and statistically significant positive correlation between C1GALT1 expression and key tumor proliferation markers across a wide range of cancer types, suggesting a potential role for C1GALT1 in promoting tumor cell proliferation." (PMID 40548474, 2025). "ABCC1 knockdown reversed C1GALT1‐mediated tumor growth by 36% in response to doxorubicin challenge." (PMID 39844613, 2025). "We established G292 sublines stably expressing a doxycycline-inducible short hairpin RNA (shRNA) targeting C1GALT1 or a control construct by lentivirus transfection and compared tumor growth rates following inoculation of NOD/Shi-scid, IL-2Rγ KO Jic (NOG) mice." (PMID 38622340, 2024). "Furthermore, microscopic examination of excised tumors revealed a substantial decrease in cell density and deformation of tumor cells by C1GALT1 knockdown." (PMID 38622340, 2024). "The mechanism of action of C1GALT1 is multifaceted and involves the regulation of target protein expression, phosphorylation, and localization, ultimately controlling various biological processes such as tumor proliferation, migration, and adhesion." (PMID 38699634, 2024). "As an increase was observed in the number of tumor‐infiltrating Granzyme B+ cells in C1galt1 knockout tumors, we further performed ex vivo CTL assays to elucidate whether the T cell‐mediated cytotoxicity was involved." (PMID 37452653, 2024). "Importantly, suppression of C1GALT1 expression not only inhibited the development and progression of the tumor itself but also attracted more macrophages and dendritic cells to the tumor microenvironment through MGL." (PMID 38662050, 2024). "As C1GalT1 controls a core O-glycosylation biosynthesis pathway, change of C1GalT1 likely alters the glycosylation status of many cell membrane proteins that are critical in tumour cell activities." (PMID 37612278, 2023).
tumor (continued). "Consistent with our in vitro discoveries, tumours formed in the C1galt1f/f/Erb mice were seen to express higher amounts of TF (12.8 ± 4.8% staining) and low levels of Tn (<1% staining) structures than those in ME C1galt1-/-/Erb mice." (PMID 37612278, 2023). "Finally, 83 out of 159 cores demonstrated that C1GALT1 protein expression was polarized towards the apical side of the tumor cell." (PMID 36745330, 2023). "Thus, C1GalT1 expression in cancer cells reciprocally controls tumour cell-cell and tumour-macrophage interactions mediated by galectin-3 and MGL with double impact on cancer development and progression." (PMID 37612278, 2023). "Thus, lower IL-6 secretion by TAMs as a result of their interaction with lower C1GalT1 expressing tumour cells will likely have a less positive influence on tumour growth in the TME." (PMID 37612278, 2023). "Interestingly, high expression of C1GALT1 in tumor tissues predicts a better prognosis in NB in our current study." (PMID 35169131, 2022). "However, the effect of C1GALT1 in CCA progression requires further study vis à vis CCA metastasis, its sensitivity to other chemotherapeutic drugs and resistance mechanism that trigger the significant role of C1GALT1 down-regulation in CCA tumor progression." (PMID 35207462, 2022). "In some tumors, C1GALT1 plays a tumor-promoting role, while in others C1GALT1 is tumor-suppressive." (PMID 35169131, 2022). "Taken together, our study showed that C1GALT1 high expression is an independent prognostic factor and predicts better survival outcomes for NB patients, complementary to age of patients, differentiation status of tumor, MYCN status, and clinical stages." (PMID 35169131, 2022). "C1GALT1 knockdown suppressed tumor growth and invasiveness in vitro and in vivo." (PMID 33420364, 2021). "C1galt1 knockout (KO) promotes tumor development and metastasis of PDAC in mice." (PMID 33420364, 2021). "Moreover, the promotion of tumor growth by C1GALT1 overexpression was mitigated by silencing of RAC1." (PMID 34307388, 2021). "To determine whether C1GALT1 could affect tumor growth in vivo, we conducted a mouse xenograft experiment." (PMID 34307388, 2021). "As activation of RTKs is often essential in tumor cell growth and development, overexpression of C1GalT1, which changes RTK glycosylation and their sensitivity to ligand binding, is therefore likely involved in regulating RTK-mediated activity in cancer development." (PMID 34944925, 2021). "Functional experiments indicated that integrin α5 inhibition could reverse C1GALT1-mediated tumor growth and metastasis both in vitro and in vivo." (PMID 34452648, 2021). "In sharp contrast, only about 5% (6/126) of PDAC tumor tissues showed lower C1GALT1 levels (T < N)." (PMID 33420364, 2021). "However, our data showed that knockdown of C1GALT1 in human PDAC cells suppressed tumor growth and metastasis in NOD/SCID mouse xenograft models." (PMID 33420364, 2021). "Additionally, C1GALT1 KO mice were crossed with PyMT, resulting in the delayed onset of tumor progression." (PMID 32075174, 2020). "The results showed that C1GALT1 knockout significantly decreased tumor growth and metastasis." (PMID 29930379, 2018). "Chi-square analysis shows that high C1GALT1 expression correlates with advanced tumor stage." (PMID 25762620, 2015). "In addition, the effect of C1GALT1 on tumor metastasis in vivo was evaluated by rectal xenograft model." (PMID 24758762, 2014). "In conclusion, this study revealed a novel mechanism by which C1GALT1 promotes tumor metastasis." (PMID 25089569, 2014). "This negative correlation suggests that higher levels of C1GALT1 expression are associated with lower levels of both Tregs and MDSCs, which may point to a potential link between C1GALT1 expression and reduced immunosuppressive cell presence within the tumor microenvironment." (PMID 40548474, 2025).
tumor (continued). "Additionally, the relations between the abundance of tumor‐infiltrating lymphocytes (TILs), especially immunosuppressive regulatory T‐cells (Tregs) and myeloid‐derived suppressive cells (MDSCs), and expression of the C1GALT1 gene were analyzed." (PMID 40548474, 2025). "However, we cannot exclude the possibility that C1GALT1 may promote ES cell viability and tumor growth, in part, through O-glycosylation of other substrates, such as integrins or receptor tyrosine kinases." (PMID 39894896, 2025). "Additionally, C1GALT1 suppression impacts tumor cell interactions and activities." (PMID 38699634, 2024). "In addition, C1GALT1 expression negatively correlated with tumor grade." (PMID 36745330, 2023). "In addition, we confirmed the prevalence of CNV alterations in ARGs in COAD patients, and CNVs seem associated with higher expression of ARGs in tumor tissues, such as NF1, COL4A2, C1GALT1, SPHK1, RUNX1, implying a potential regulatory role of CNVs on the expression of ARGs." (PMID 36505481, 2022). "In addition, overexpression or knockdown of C1GALT1 could facilitate or suppress tumor growth in vivo." (PMID 34307388, 2021). "Next, we assessed whether C1GALT1 inhibitor itraconazole could also suppress tumor growth." (PMID 29930379, 2018). "IHC analysis of ES patient tumor samples confirmed high levels of SMO and GLI1, which correlated with high C1GALT1 expression." (PMID 39894896, 2025). "Intriguingly, in mouse models with lower tumor C1GALT1 expression, more MGL-expressing macrophages and dendritic cells were attracted into the tumor surroundings." (PMID 38662050, 2024). "Intriguingly, nearly all signature-related genes were significantly downregulated in the tumor tissue in both the TCGA and local cohort, except DDN and C1GALT1." (PMID 37735483, 2023). "In this study, the galectin-3-mediated tumour cell-cell homotypic aggregation and promotion of EGF-induced EGFR activation are seen to be significantly reduced following C1GalT1-suppression." (PMID 37612278, 2023). "In the meantime, C1GalT1 suppression substantially increased MGL-mediated macrophage-tumour cell interaction and macrophage-tumour cell phagocytosis and cytokine secretion." (PMID 37612278, 2023). "As both macrophages and DCs play a crucial role in immune surveillance, high C1GalT1 expression in tumour cells, which leads to lower abundance of cell surface Tn antigen, would reduce MGL-mediated tumour cell interaction with macrophages and DCs." (PMID 37612278, 2023). "This indicates that tumours with lower C1GalT1 expression attract more MGL-expressing macrophages and dendritic cells into the tumour microenvironment." (PMID 37612278, 2023). "Immunohistochemical analyses revealed decreased T antigen and C1GALT1 expression and cell proliferation, and enhanced apoptosis, in ITZ-treated and C1GALT1-silenced tumor xenografts." (PMID 35864552, 2022). "C1GALT1 high expression is an independent prognostic factor for better survival outcomes in NB patients, and could provide complementary prognostic information in addition to age of patients, differentiation status of tumor, MYCN amplification status, and clinical stages." (PMID 35169131, 2022). "The results indicated that high C1GALT1 expression correlated with advanced cancer (stages III and IV), higher histological grade, advanced tumor invasion, and nodal metastasis." (PMID 32005975, 2020). "In contrast, overexpression of C1GALT1 promoted MCF-7 tumor growth and tumor weight compared with mock." (PMID 25762620, 2015). "Here, we demonstrated that C1GALT1 increased HCC cell adhesion, migration, and invasion in vitro, and enhanced tumor metastasis in vivo." (PMID 25089569, 2014). "Results showed that overexpression of C1GALT1 in SW480 cells increased tumor weights, whereas knockdown of C1GALT1 in SW620 cells decreased tumor weights." (PMID 24758762, 2014).